LPAR5 (lysophosphatidic acid receptor 5)
Description:
Receptor for lysophosphatidic acid (LPA), a mediator of diverse cellular activities.
Synonyms: GPR92; GPR93; KPG_010; LPA5
Tractability: Small molecule: a high-quality ligand is known; it belongs to a druggable protein family. Antibody: its Gene Ontology location is reachable by antibodies, with high confidence; UniProt places it where antibodies can reach, with medium confidence; UniProt predicts a signal peptide or a membrane-spanning region. PROTAC: a small molecule that binds it is known.
Target class: EDG receptor; Family A G protein-coupled receptor; Lipid-like ligand receptor (family A GPCR); Membrane receptor; Small molecule receptor (family A GPCR)
Gene: Protein-coding gene on chromosome 12 (6,618,835 to 6,636,444, reverse strand). Ensembl gene ENSG00000184574.
Subcellular location: Cell membrane
Pathways (Reactome):
Signal Transduction: G alpha (i) signalling events; G alpha (q) signalling events; Lysosphingolipid and LPA receptors
Gene Ontology:
Molecular function: G protein-coupled receptor activity
Biological process: behavioral response to pain; G protein-coupled receptor signaling pathway
Cellular component: plasma membrane; membrane
Genetic constraint (gnomAD): Loss-of-function variants: 0 observed, 0.95 expected, observed/expected ratio (o/e) 0, 90% interval 0 to 1.74. That is too few expected variants to judge how well the gene tolerates losing a copy. Missense variants: 544 observed, 474.32 expected, observed/expected ratio (o/e) 1.15, 90% interval 1.07 to 1.23. Synonymous variants: 271 observed, 236.24 expected, observed/expected ratio (o/e) 1.15, 90% interval 1.04 to 1.27.
Homologues: Orthologues: chimpanzee LPAR5 (99% identical), macaque LPAR5 (95% identical), rabbit LPAR5 (85% identical), mouse Lpar5 (81% identical), dog LPAR5 (80% identical), rat Lpar5 (80% identical), pig LPAR5 (78% identical), tropical clawed frog lpar5 (46% identical), zebrafish lpar5b (28% identical), zebrafish lpar5a (27% identical). Paralogues in human: GPR68 (25% identical).
Diseases named in the same sentence as LPAR5 in open-access papers:
LPAR5 is named in the same sentence as 68 diseases in open-access papers, as found by Europe PMC text mining. Sharing a sentence is not in itself a finding about the gene and the disease. The quoted sentences say what the papers report.
melanoma (15 papers, 2011 to 2023). A malignant, usually aggressive tumor composed of atypical, neoplastic melanocytes. "Previously, we have shown that LPAR5-deficient CD8 T cells are better able to kill melanoma tumor cells in vitro and control local tumor growth after implantation and compared to wildtype CD8 T cells." (PMID 37270644, 2023). "Overall, Lpar5−/− OT-I CD8 T cells responding to melanoma in vivo display fewer inhibitory receptors and improved anti-tumor immunity." (PMID 37270644, 2023). "Similar to this study, researchers have demonstrated that LPAR5 plays an important role in melanoma invasion and metastasis." (PMID 36199069, 2022). "In a separate study, the incidence of B16F10 melanoma-derived lung metastases were found to be reduced by 85% in Lpar5−/− mice." (PMID 32397679, 2020). "In a mouse melanoma model we have reported that melanoma-specific Lpar5−/− CD8 T cells are better able to control tumor growth compared to wild type melanoma-specific CD8 T cells." (PMID 31231367, 2019). "Since we observed decreased Tim3 expression on PD1+Lpar5−/− OT-I CD8 T cells isolated from melanoma tumors compared to wildtype OT-I CD8 T cells, we sought to further investigate how LPA signaling might modulate exhausted and/or dysfunctional phenotypes." (PMID 37270644, 2023). "LPAR5 was found to act as an anti-migratory receptor via cAMP-PKA pathway in B16 melanoma cells." (PMID 36591220, 2022). "Knockout of LPAR5 significantly reduces melanoma-derived lung metastases in mice." (PMID 36199069, 2022). "LPAR5 expression is markedly increased in long-term cisplatin-treated melanoma cells." (PMID 34209775, 2021). "In addition to our finding that PCa patients in the high LPAR5 expression group had worse survival, other LPAR subtypes were associated with poor survival such as LPAR1 in melanoma, LPAR2 in adrenocortical carcinoma, LPAR3 in pancreatic cancer, and LPAR4 in renal papillary carcinoma." (PMID 36806315, 2023). "Moreover, depletion of LPAR5 in murine B16-F10 melanoma resulted in fewer lung metastasis." (PMID 34209775, 2021). "Moreover, depletion of LPAR5 in murine B16-F10 melanoma resulted in fewer lung metastasis, suggesting pharmaceutic inhibition of LPAR5 may also manage melanoma-mediated metastasis." (PMID 34209775, 2021). "In the C57BL/6-B16-F10 syngeneic murine melanoma lung metastasis model, we previously demonstrated that host LPAR1 and LPAR5 promote the seeding of metastases and that ATX produced by cancer cells enhances melanoma cell migration and invasion." (PMID 35326737, 2022). "Reversely, proliferation and/or motility of cancer cells also showed a decrease after LPA signalling through LPAR2 in melanoma, LPAR4 in pancreatic, colon, and head and neck cancer, LPAR5 in pancreatic cancer and melanoma, and LPAR6 in colon cancer." (PMID 34722305, 2021). "Specifically, TILs derived from three melanoma patients predominantly expressed LPAR6 with low expression of LPAR2, whereas peripheral CD8+ T cells expressed LPAR6 > LPAR2 > LPAR5 > LPAR4." (PMID 32397679, 2020). "This conclusion is further supported by the ability of Lpar5−/− mice and Lpar5−/− tumor-specific CD8 T cells to better control EG7 lymphoma and B16 melanoma growth, respectively, compared to wild type." (PMID 31231367, 2019). "We intravenously injected syngeneic mouse melanoma B16 cells expressing chicken ovalbumin (B16.cOVA, surrogate tumor antigen) into wildtype C57BL/6 hosts and on the same day adoptively transferred wildtype or Lpar5−/− OT-I CD8 T cells into the same host mice." (PMID 37270644, 2023). "The mechanism of LPA-dependent homing of lymphocytes into sites of metastasis is not clear, although the involvement of LPAR1, LPAR5 in the seeding of B16 melanoma-derived lung metastasis has been demonstrated using knockout mice for these LPAR subtypes." (PMID 32397679, 2020).
melanoma (continued). "These in vitro data were further supported by in vivo observations that adoptive transfer of CD8+ T cells isolated from Lpar5−/− mice were more effective at reducing the growth rate of both EG7 lymphoma and B16F10 melanoma tumors compared to wild type CD8+ T cells." (PMID 32397679, 2020). "LPA5 activation in CD8+ T cells suppresses T-cell activation and proliferation, and Lpar5−/− CD8+ T cell transfer suppresses tumor growth in a mouse model of melanoma." (PMID 31323936, 2019).
thyroid cancer (11 papers, 2018 to 2024). "Lysophosphatidic acid receptor 5 (LPAR5) overexpression is involved in mediating thyroid cancer progression; however, the mechanism underlying this process requires further elucidation." (PMID 37324256, 2023). "Recent studies on PTC have shown that LPAR5 is associated with progression and overall survival in thyroid cancer, which is consistent the findings presented in our study." (PMID 34115774, 2021). "Multivariate analysis demonstrated that miR-184, miR-146b, miR-509-3 and LPAR5 were an independent risk factors for prognosis, and they have the potential to be the targets for treatment of thyroid cancer." (PMID 29740512, 2018). "For example, knocking down LPAR5 can inhibit thyroid cancer through the PI3K/Akt/mTOR signaling pathway." (PMID 39671369, 2024). "Knockdown of LPAR5 promotes thyroid cancer (PTC) cell apoptosis and reduces proliferation through the PI3K-Akt pathway." (PMID 36199069, 2022). "Blocking LPAR5 in thyroid cancer with a selective LPA5 antagonist TCLPA5 attenuated cancer proliferation and migration via PI3K/Akt signaling in vivo and in vitro." (PMID 34209775, 2021). "MiR-146b, miR-184, miR-767, miR-6730, miR-6860, miR-196a-2, miR-509-3 and LPAR5 were correlated with the overall survival of thyroid cancer patients." (PMID 29740512, 2018). "Furthermore, LPAR5 promotes the proliferation and migration of thyroid cancer cells by activating the PI3K p110β subunit and subsequently AKT/mTOR/S6K1 signalling." (PMID 38607068, 2024). "Among the hub genes identified from PPI network, LPAR5 may play important roles in thyroid cancer." (PMID 29740512, 2018). "In thyroid cancer cells, the trinucleotide repeat-containing adaptor 6C-antisense 1 (TNRC6C-AS1) regulates the expression of LPAR5." (PMID 38607068, 2024). "Only CTHRC1 and LPAR5 were upregulated and MAGI1 was downregulated in lung adenocarcinoma, thyroid carcinoma, and kidney and renal papillary cell carcinoma in addition to invasive breast cancer when these genes were queried from TCGA database." (PMID 32539762, 2020). "LPAR5 antagonist TCLPA5 attenuated cancer proliferation and migration in thyroid cancer." (PMID 34209775, 2021). "LPAR5 is one of the LPA receptor members, of which LPAR1 had been explored in glioma, but LPAR5 had been researched in promoting fibrosarcoma and thyroid cancer." (PMID 33408717, 2020). "Although the specific biological functions of BCL2 and LPAR5 genes in PTC had not been explored directly by molecular biology methods, data mining based on bioinformatics tools had also confirmed that BCL2 gene was down-regulated in PTC, and LPAR5 gene was up-regulated in thyroid cancer." (PMID 30872410, 2019).
papillary thyroid carcinoma (7 papers, 2020 to 2025). "In papillary thyroid carcinoma, the LPAR5 is associated with immune infiltration." (PMID 33408717, 2020). "LPAR5 promotes the progression of papillary thyroid carcinoma (PTC), though its immune-related roles remain underexplored." (PMID 40340807, 2025). "LPAR5 is upregulated in papillary thyroid carcinoma (PTC), and downregulation of LPAR5 decreases the proliferation and migration phenotype via the PI3K/Akt pathway." (PMID 36199069, 2022).
psoriasis (7 papers, 2020 to 2024). An autoimmune condition characterized by red, well-delineated plaques with silvery scales that are usually on the extensor surfaces and scalp. "The activation of LPAR5 on immune cells was related with NLRP3 inflammasome activation during psoriasis development." (PMID 36837912, 2023). "A contribution of keratinocytes would also explain the rather weak differences in calcium fluxes in the DRG cultures of Advillin-LPAR5−/− versus LPAR5-flfl cultures, agreeing with a recent study, in which LPAR5-mediated signaling of keratinocytes was shown to drive the pathogenesis of psoriasis." (PMID 39125747, 2024). "Taken together, we suggest that LPA-induced keratinocyte proliferation could be one of the mechanisms underlying psoriasis development and combination therapy targeting LPAR1 and LPAR5 might be one of the options for psoriasis treatment." (PMID 34639115, 2021). "It is noteworthy that LPAR5 can activate NLRP3 inflammasome in macrophages and contribute to imiquimod-induced psoriasis-like lesions." (PMID 34662522, 2021). "It is worthy of note that LPAR5 can activate NLRP3 inflammasome in macrophages and contribute to imiquimod-induced psoriasis-like lesions." (PMID 34662522, 2021). "Recently, lysophosphatidic acid (LPA)/LPAR5 signaling has been reported to be involved in both NLRP3 inflammasome activation in macrophages and keratinocyte activation to produce inflammatory cytokines, contributing to psoriasis pathogenesis." (PMID 34639115, 2021). "Moreover, LPAR5 is involved in NLRP3 inflammasome activation in macrophages of psoriatic lesions and also keratinocyte activation to produce inflammatory cytokines, contributing to psoriasis pathogenesis." (PMID 34639115, 2021).
pancreatic cancer (5 papers, 2020 to 2023). "It has been shown that LPAR5 is related to the pathogenesis of pancreatic cancer." (PMID 32766727, 2020). "For example, LPAR5 is mainly expressed in stomach, colon and pancreatic cancer, while LPAR3 and LPAR4 are predominantly expressed in pancreatic cancer." (PMID 37550785, 2023).
lung carcinoma (4 papers, 2017 to 2023). "Through this study, we found that LPAR5 is an important molecule affecting the migration of cervical cancer cells and lung cancer cells and is significantly associated with IR-induced EMT." (PMID 36199069, 2022). "Taken together, these data indicate that dysregulation of the ATX/LPA/LPAR5 axis contributes to PD-1 blockade therapy resistance in KP mutant lung cancer, and cotargeting this immunosuppressive axis efficaciously controls lung cancer progression and metastasis." (PMID 37655662, 2023).
sarcoma (4 papers, 2018 to 2022). A usually aggressive malignant neoplasm of the soft tissue or bone. "Additionally, LPAR5 negatively regulated cell motile and invasive activities of human sarcoma cell lines." (PMID 29740512, 2018).
non-small cell lung carcinoma (3 papers, 2023 to 2025). A group of at least three distinct histological types of lung cancer, including non-small cell squamous cell carcinoma, adenocarcinoma, and large cell carcinoma. "LPAR5 stimulates the proliferation and migration potential of non-small-cell lung cancer (NSCLC) by positively regulating MLLT11." (PMID 39671369, 2024).
Obesity (3 papers, 2017 to 2022). Accumulation of substantial excess body fat. "Lysophosphatidic acid receptor 5 (LPAR5), the most recently found member of the LPAR family, is a G protein-coupled transmembrane receptor that play a crucial role in various disease, such as cardiovascular disease, airway disease, obesity and cancer." (PMID 34662522, 2021).
osteosarcoma (3 papers, 2022 to 2025). A usually aggressive malignant bone-forming mesenchymal neoplasm, predominantly affecting adolescents and young adults. "Some studies have reported the association of LPAR5+ macrophages with osteosarcoma prognosis, but comprehensive analyses of key molecules in the glycerolipid metabolic pathway remain limited." (PMID 41502512, 2025). "What’s more, LPAR5 expression was much higher in primary osteosarcoma patients than metastasis patients and recurrent patients." (PMID 36591220, 2022). "We analyzed the impact of LPAR5 on the prognosis of osteosarcoma patients by metastasis-free survival as defined by the authors of the dataset." (PMID 36591220, 2022). "In GSE12512 dataset, the expression of LPAR5 was higher in tumor tissue than in osteosarcoma cell line (P<0.001)." (PMID 36591220, 2022). "Through subsequent research and analysis, we found that LPAR5 was a promising indicator for TME remodeling with a prognostic value for osteosarcoma." (PMID 36591220, 2022). "There was only one study reported that the motile activity of osteosarcoma cells was inhibited by LPAR5 knockdown, which was the opposite of our results." (PMID 36591220, 2022). "LPAR5+ macrophages among primary, metastasis and recurrent osteosarcoma patients." (PMID 36591220, 2022). "Particularly, LPAR5+ macrophages might have great potential to be a prognostic factor and therapeutic target for osteosarcoma." (PMID 36591220, 2022). "And the expression of LPAR5 was positively correlated with immune cells, especially macrophages, indicating LPAR5+ macrophages played an important role in tumor microenvironment of osteosarcoma." (PMID 36591220, 2022). "In our study, we identified LPAR5+ macrophages that were present in the tumor tissue, and higher expression predicted a better prognosis, which would provide a new insight into prognosis assessment and immunotherapy of osteosarcoma." (PMID 36591220, 2022). "In the present study, we found that LPAR5 expression was positively correlated with overall survival and negatively correlated with metastasis, indicating LPAR5 might be protective factors for osteosarcoma patients." (PMID 36591220, 2022). "In addition, the expression of LPAR5 was higher in tumor tissue than in osteosarcoma cell line." (PMID 36591220, 2022). "LPAR5 was identified as a potential indicator for TME remodeling and a therapeutic target for osteosarcoma based on scRNA-seq data." (PMID 39324133, 2024). "We identified a TME-related gene, LPAR5, which is a promising indicator for TME remodeling in osteosarcoma." (PMID 36591220, 2022). "In this study, we analyzed the TME of osteosarcoma using ESTIMATE and CIBERSORT algorithms and screened out a TME-related gene, LPAR5, which is a promising indicator for TME remodeling in osteosarcoma." (PMID 36591220, 2022). "Through protein-protein interaction (PPI) network and univariate Cox regression analysis based on shared DEGs, we screened out and validated a TME-related core gene, LPAR5, which may be a promising indicator for TME remodeling with a prognostic value in osteosarcoma." (PMID 36591220, 2022).
Anxiety (2 papers, 2020 to 2024). Intense feelings of nervousness, tension, or panic often arise in response to interpersonal stresses. "Signs of reduced anxiety were revealed in the LPAR5-deficient mice after several exploratory tasks." (PMID 32325720, 2020). "Surprisingly, the observed anxiety-like phenotype found in LPAR1-deficient mice and the current results were opposite to the observed anxiolytic phenotype in LPAR5-deficient mice." (PMID 32325720, 2020).
glioma (2 papers, 2020). A benign or malignant brain and spinal cord tumor that arises from glial cells (astrocytes, oligodendrocytes, ependymal cells). "The analysis of TCGA LGG revealed that patients whose glioma expression high or low of LPAR5 had different outcomes, and consistent with LPAR5, the expression of other five genes all had a relationship with outcomes." (PMID 33408717, 2020). "The expression of CD163 and LPAR5 protein were lower in normal brain than glioma." (PMID 33408717, 2020). "The function of LPAR5 in glioma still unclear, further research is still necessary." (PMID 33408717, 2020). "Through high-throughput expression profiling, WGCNA, lasso, and multivariate Cox analysis, we acquired eight genes (HCK, HAVCR2, CD37, LPAR5, NAGA, C1QC, FCER1G and AIF1) to construct the MRGs signature in Grade II/III glioma patients." (PMID 33186124, 2020).
nasopharyngeal carcinoma (2 papers, 2018 to 2022). A carcinoma arising from the nasopharyngeal epithelium. "LPAR5 was also found down-regulated in primary nasopharyngeal carcinoma, and the downregulation of LPAR5 promoted the LPA-induced migration of nasopharyngeal carcinoma cell lines." (PMID 36591220, 2022). "LPAR5 was down-regulated in primary undifferentiated nasopharyngeal carcinoma and promoted the LPA-induced migration of nasopharyngeal carcinoma cell lines." (PMID 29740512, 2018).
Stroke (2 papers, 2022 to 2025). Sudden impairment of blood flow to a part of the brain due to occlusion or rupture of an artery to the brain. "In photothrombotic stroke models, PARP14 overexpression suppresses LPAR5 (lysophosphatidic acid receptor 5)-dependent inflammatory signaling, reduces microglial activation, and enhances macroautophagic flux." (PMID 41007413, 2025).
asthma (1 paper, 2021). "Asthma also induced detectable LPAr5 mRNA levels within the carotid body." (PMID 34465362, 2021).
atopic dermatitis (1 paper, 2021). "In skin diseases, however, LPA acts as a pruritogenic mediator through LPAR1 in atopic dermatitis model and induces itch through LPAR5." (PMID 34639115, 2021).
Bovine mastitis (1 paper, 2023). INFLAMMATION of the UDDER in cows. "For instance, the differential expression of genes (CX3CR1, RHOH, LPAR5, and GATA3) overlapped with dMHB discriminant signatures related to SC subclinical mastitis have been found relevant to immune responses to bovine mastitis." (PMID 37373515, 2023).
colon adenocarcinoma (1 paper, 2022). "In Colon adenocarcinoma (COAD), Prostate adenocarcinoma (PRAD), LPAR5 was highly expressed in normal tissue." (PMID 36591220, 2022).